HIF1A (hypoxia inducible factor 1 subunit alpha)
Diseases named in the same sentence as HIF1A in open-access papers (continued):
Sharing a sentence is not in itself a finding about the gene and the disease.
tumor (continued). "Hypoxia attenuates anti‐tumour immunity by upregulating the expression of PD‐L1 on tumour cells, MDSCs, TAMs and DCs via HIF‐1α regulated pathways." (PMID 35466515, 2022). "To gain further insight into how HIF1α induces CRC progression, we examined the effect of HIF1α on many microenvironmental genes, including TGF-β, TNF-α, VEGF, EGF, PDGF, b-FGF, HGF, and IGF, which have been implicated in promoting tumor development." (PMID 35355718, 2022). "Luminal A-like tumours were the largest subgroup with 552 tumours and 22% of these were HIF-1α positive, while luminal B tumours had a 30% frequency of HIF-1α positivity (76 of 257)." (PMID 35140341, 2022). "The implication of HIF-1α in tumor-promoting inflammation, immunosuppression, and metastasis has been documented in different cancer models in relation to hypoxia." (PMID 36496973, 2022). "In VHL-deficient and hypoxic ccRCC tumor cells, protein kinase growth arrest-specific 6 (GAS6)/AXL is activated by HIF1A and HIF2A." (PMID 35659268, 2022). "HIF1A is a hypoxia inducible factor, and its absence increases tumor aggressiveness and metastatic activity." (PMID 35127830, 2022). "HIF-1α promotes the M2 phenotype of macrophages and tumor survival, thus limiting the effectiveness of PDT." (PMID 36338755, 2022). "In conclusion, in LUAD cells, highly expressed mPRα enhances the activation of cAMP/JAK/STAT3 signaling and increases HIF1α-induced VEGF secretion into the tumor microenvironment, promoting HUVEC migration and tube formation under hypoxia." (PMID 35123491, 2022). "In the past two decades, the mechanism of tumor hypoxia has become more understandable with the discovery of hypoxia-inducible factor-1α (HIF-1α)." (PMID 36014432, 2022). "This is to say, the role of HIF-1α in tumor and non-tumor groups and ACP populations is inconsistent." (PMID 36091021, 2022). "Pyruvate dehydrogenase activity and cell viability were analyzed to determine the contribution of the AMPK/HIF1α‐mediated cascade to the glycolytic phenotype and tumor cell progression induced by SCT‐1015." (PMID 35298869, 2022). "RT also induces HIF-1α which induces PD-L1 expression in tumor cells and TAMs, leading to resistance to RT and immunosuppression." (PMID 36532071, 2022). "Collectively, these results demonstrate that the expression level of HIF1α is associated with the pathological staging of LIHC, which has a certain guiding significance for guiding the pathological staging of this tumor." (PMID 35860430, 2022). "An increased PD-L1 expression in tumor cells is also induced by the release of hypoxia-inducible factor 1-alpha and 1-beta (HIF-1a and HIF-1b)." (PMID 35222642, 2022). "Similar to the effects of wortmannin, Glut‐1 or HIF‐1α knockout enhanced the anti‐proliferative effect of 12 Gy, with the fewest proliferating cells observed in Glut‐1 and HIF‐1α double knockout tumours following irradiation." (PMID 35415942, 2022). "Under hypoxia conditions, HIF-1α is upregulated in T cells, which subsequently inhibits PGC1α activation to damage T-cell anti-tumor function." (PMID 36618408, 2022). "Tumor–derived exosomal miR-301a-3p, which is regulated by HIF-1α and HIF-2α, can be transferred to TAMs, promoting tumor cell EMT, migration, invasion, and metastatic potential." (PMID 36071472, 2022). "Since M1 macrophages have cytotoxic activity on cancer cells, the HIF-1α/miR-30c/REDD1/mTOR axis was suggested as a mechanism for hypoxia-induced suppression of anti-tumor immunity in GC." (PMID 35681691, 2022). "In this study, both in vitro and in vivo experiments revealed that metformin inhibited OC cell proliferation, the proportion of CD44+/CD117+ CSCs, tumor growth, and HIF-1α expression." (PMID 36046821, 2022). "HIF-1α induces an immunosuppressive tumour microenvironment by recruiting Tregs, MDSCs and macrophages." (PMID 36429126, 2022). "HIF-1α activity has been found to reduce the tumour burden in ccRCC xenograft models, while HIF-2α promotes tumour growth." (PMID 35158796, 2022).
tumor (continued). "HIF-1α has a very important role in tumor growth, angiogenesis, proliferation, motility, invasion, and metastasis." (PMID 35733918, 2022). "HIF1α then interacts with transcriptional co-activators and binds to transcriptional response elements on DNA, resulting in the expression of pro-tumor progression and metastasis genes, including GΜLT-1 and VEGFA." (PMID 36473847, 2022). "The modulation of both VEGF expression and tumor angiogenesis is also driven by molecules belonging to HIF1α and insulin-like growth factor 1 (IGF1)/insulin-like growth factor 1 receptor (IGF1R) signaling." (PMID 36432658, 2022). "Subcutaneous or orthotopic tumor models established from TMK-1 cells with a dominant-negative form of HIF-1α were significantly smaller." (PMID 35681691, 2022). "In solid tumors, the mitochondrial-mediated production of ROS supplements tumor growth via HIF-1α signaling." (PMID 35592530, 2022). "Reprogramming of the glucose flux is critical in establishing the tumor microenvironment, since it results in the elevation of the HIF-1α levels in response to hypoxia in rapidly growing cancer cells." (PMID 35563687, 2022). "HIF-1α is a classical transcription factor that regulates the expression of many oncogenic factors and tumor suppressors." (PMID 35712504, 2022). "HIF1α, which is significantly up-regulated under hypoxia, is a critical regulatory factor of hypoxia metabolism in tumor cells." (PMID 35692750, 2022). "In the present study, “pseudo-papillary” structures containing nestin+/FOXM1+ cells in the perivascular niche and CA9/HIF-1α positivity in the area surrounding stem cell accumulation resembled co-opted tumor vessels and were observed in refractory-Bev." (PMID 35785200, 2022). "In EGFR-mutant tumor cells cocultured with activated PBMCs, EGFR-TKI treatment increased CXCL10 in the supernatant; this activated CXCR3 in the tumor cells to induce the phosphorylation of Src and the NF-κB subunit, p65, and the expression of HIF-1α." (PMID 36612121, 2022). "Lactate increases HIF-1α stability and VEGF release from tumor-associated stromal cells, and also activation of NF-κB and PI3K signaling in endothelial cells." (PMID 36419156, 2022). "Since the autocrine loop within TAMs originates in tumor cells, demonstrated by the effects of tumor supernatants on the TAMs, further analysis of the molecular factors upstream of HIF1α pathway activation should also be identified." (PMID 35362482, 2022). "HIF-1α has been identified as a key regulator of proliferative, invasive, and immunosuppressive mechanisms that favor tumor progression." (PMID 36496973, 2022). "Taken together, Piezo1 can respond to various mechanical forces to facilitate tumor angiogenesis by activating the HIF-1α pathway and promoting MMPs expression." (PMID 36230880, 2022). "Abnormal HIF/VEGFA signaling is a key facilitator of tumor angiogenesis, in which HIF1β plays a critical role in a HIF1α-independent manner." (PMID 35740507, 2022). "An early study also demonstrates that administration of the antioxidant NAC suppresses tumor incidence in mice by inhibiting HIF1a-driven tumor growth." (PMID 36154922, 2022). "Sirt3 suppression in primary mouse embryo fibroblasts (MEFs) or tumor cell lines stimulates cell proliferation and augments HIF1α protein stabilization and its transcriptional activity under hypoxic conditions." (PMID 35938164, 2022). "We found that most tumour samples from surgically removed IBTRs had the same HIF-1α status as their corresponding primary tumour, indicating that hypoxia and HIF-1α positivity is an inherent tumour trait." (PMID 35140341, 2022). "Several genes have been proven to play crucial roles in tumor angiogenesis by directly acting on VEGF or stimulating angiogenesis through HIF-1α/VEGF pathway." (PMID 36347835, 2022). "MMP-9 and HIF-1α expressing neutrophils were shown to be the main tumor-infiltrating cells that promoted angiogenesis and significantly contributed to the NIP pathogenesis." (PMID 35158807, 2022).
tumor (continued). "CircRNF20 is a 499 bp circular RNA derived from RNF20 Gene that can promote tumor progression via miR-487a/HIF-1α/HK2 in BC." (PMID 36532768, 2022). "Analyses of the non-irradiated patient group, as well as the total study population, showed that patients with HIF-1α positive primary tumours were more prone to develop IBTR during the first five years after surgery." (PMID 35140341, 2022). "A previous study showed that SIRT3 exerts tumor suppressive effects by suppressing ROS and regulating HIF-1α." (PMID 36211825, 2022). "IL-6 also promotes the production of HIF-1α and enhances the self-regulation of Tregs in the process of tumor microenvironment (TME) formation." (PMID 35927985, 2022). "Since HIF-1α plays an important role in tumor progression, we also summarize the current drugs that inhibit tumor progression by modulating HIF-1α." (PMID 36139386, 2022). "IL-1β, highly secreted by macrophages, enhances tumor cell metastasis through HIF1α signals under hypoxic TME in the liver and breast mouse cancer model." (PMID 35281061, 2022). "HIF-1α is overexpressed in proximity to the necrotic tumor core which is poorly vascularized and deprived of oxygen supply." (PMID 35619923, 2022). "Numerous studies have reported that the expression of many genes in the microenvironment of tumor growth is subject to hypoxia-inducible factor- (HIF)-1α-activated transcription." (PMID 35733918, 2022). "Tumor progression is associated with intratumor hypoxia, which leads to increased vascular density, and HIF-1α is a transcription factor that allows for adaptation of tumor cells to hypoxia." (PMID 35406582, 2022). "It has been reported that the NRP1 promoter can directly bind to HIF-1α, which is a critical tumor driver involved in PI3K/AKT regulation and can facilitate the upregulation of both HIF-1α and PI3K/AKT through a positive feedback loop." (PMID 35281516, 2022). "This mild hyperthermia can enhance oxygen levels in tumors and decrease HIF-1α expression so as to alleviate tumor hypoxia and reverse hypoxia-induced radio-resistance." (PMID 36559162, 2022). "Von Hippel–Lindau (pVHL), which also acts as a tumor suppressor, binds the ubiquitin ligase complex E3, that targets HIF-1α subunit destruction in O2-dependent degradation domain." (PMID 35205167, 2022). "The reduction in HIF‐1α induced by Glut‐1 knockout was also found in tumour tissues, and the detailed mechanism requires further investigation." (PMID 35415942, 2022). "This indicates that HIF-1α can promote tumour cell resistance against radio- and chemo-therapies by induction of glycolysis." (PMID 36076967, 2022). "In consideration of deep penetration of NIR-II light, we also evaluated the expression of hypoxia and apoptosis biomarker (HIF-1α and caspase-3, respectively) at the molecular level in different thickness of tumor tissue." (PMID 35277519, 2022). "HIF-1α has the potential to serve as a tumor marker for predicting the prognosis of digestive system malignancies." (PMID 35845307, 2022). "On the other hand, tumor-suppressive lncRNAs such as CF129 or LET are inhibited by HIF-1α-mediated histone deacetylase (HDAC) recruitment." (PMID 35625948, 2022). "It was able to reduce VEGF expression, inhibit HIF-1α accumulation in tumor cells, and modulate ROS generation in endothelial cells." (PMID 35662936, 2022). "The volume and weight of transplanted tumor were measured to evaluate the effect of HIF-1α gene on tumor formation in nude mice." (PMID 35664561, 2022). "The IRE1α/XBP1 pathway was shown to promote breast cancer progression and tumor initiation by activating the hypoxia pathway governed by HIF-1α." (PMID 35349489, 2022). "The stabilization of HIF-1α upregulates the expression of Programmed death-ligand 1 (PD-L1) in hypoxic tumor cells as well as the immune checkpoint V-Domain Ig suppressor of T cell activation (VISTA) in hypoxic myeloid-derived suppressor cells (MDSCs)." (PMID 35910347, 2022).
tumor (continued). "Sestrin2 can impair several dimensions of tumor cells biology by downregulating HIF-1α including angiogenesis, metastasis, and immune evasion." (PMID 35527284, 2022). "Intratumoral analysis showed that tumor areas with high levels of hypoxia, as indicated by staining of HIF1α, displayed markedly reduced CD8+ T cell infiltration as well as IFNγ expression compared to low hypoxic areas." (PMID 35840558, 2022). "The HIF1A inhibitor PX-478 suppresses tumor growth, induces cell cycle arrest in G2 phase, promotes cancer cell apoptosis, and reduce expression of COX-2 and PD-L1." (PMID 35659268, 2022). "A better understanding of the molecular mechanisms and biological functions of lncRNAs and HIF-1α will help find new effective anticancer strategies and novel tumor markers." (PMID 35819532, 2022). "Elevated HIF-1α results in a feedforward loop between the insulin growth factor (IGF)-1 receptor, HIF-1α, and caveolin-1 to facilitate tumor progression and glycolysis." (PMID 36465353, 2022). "HIF-1α has been demonstrated to play an critical role in tumor angiogenesis, cell proliferation and growth, and energy metabolism." (PMID 36536346, 2022). "This study demonstrated the safety, antitumor effect, potential as a radiation sensitizer, and tumoral hypoxia/HIF-1α suppression effect of oral administration of NBO2 water in vivo in a tumor-bearing mouse model." (PMID 35743281, 2022). "Hypoxia stabilizes HIF-1α, which triggers tumor cells to produce more vascular endothelial growth factor (VEGF)." (PMID 35402264, 2022). "In turn, the generated O2 improved the cytotoxicity and anti-tumor migration effect of CS-1 by downregulating HIF-1α and MMP-9 levels." (PMID 36424589, 2022). "HIF-1α performs a pivotal function in tumor cell invasion, metastasis, immortalization, and tumor angiogenesis." (PMID 35953863, 2022). "Tumor microenvironmental hypoxia induces the HIF-1α-dependent overexpression of PLK4, AURORA A, and CYCLIN D, resulting in CA in a wide range of cancer types." (PMID 36012111, 2022). "Although there are many markers to assess hypoxia in tumours, such as HIF-1α, X-Box Binding Protein 1 (XBP1), GLUT1 and Vascular endothelial growth factor (VEGF), the results however have been conflicting in various studies." (PMID 35659359, 2022). "Tumor cells are able to adapt to hypoxic conditions through the stabilization of hypoxia-inducible transcription factor (HIF-1α), which leads to the upregulation of several genes involved in cellular proliferation and angiogenesis." (PMID 35461243, 2022). "Although highly expressed HIF-1α enhances tumor survival, invasion, and migration by regulating cellular metabolism in the tumor’s hypoxic microenvironment, HIF-1α also can perform as an antineoplastic factor under particular circumstances." (PMID 36364008, 2022). "Given that HIF-1α plays a critical role in tumor formation, research into targeted HIF-1α therapy is presently a trending topic." (PMID 36139386, 2022). "It has been found that deletion of HIF1A slows down primary tumor growth, and decreases the spreading of cancer cells to the bones while increasing lung metastasis." (PMID 36139678, 2022). "Knocking down of WDR72 was efficient to suppress the growth and metastasis of LCSCs and deterred tumor growth in BALB/c nude mice via regulating the AKT/HIF-1α signaling pathway." (PMID 36385964, 2022). "We conducted spheroid formation assays, which demonstrated the therapeutic effect of co-targeting STAT3 and AKT to inhibit HIF-1α signaling and decrease tumor growth in combination with cisplatin treatment." (PMID 35236823, 2022). "HIF-1α has been shown to be upregulated in various solid malignancies, with upregulation often corresponding to tumor malignancy." (PMID 36115843, 2022). "In parallel, we treated both strains with vehicle or LEM to measure the impact of tumor cell–intrinsic Hif1a or Pdl1 on tumor growth in response to LEM treatment." (PMID 35239514, 2022).
tumor (continued). "Lactate mediates partial crosstalk between tumor cells and macrophages, and also promotes the secretion of IL-6 and upregulates the expression of HIF1α." (PMID 36686771, 2022). "Results from in vivo assays proved that GSK3α-mediated tumorigenesis and tumor angiogenesis is dependent on levels of HIF1α expression." (PMID 35292059, 2022). "In HCC tumor tissues, PD-L1 is produced in a HIF-1α-dependent manner by macrophages with a high glycolytic phenotype." (PMID 36686771, 2022). "In this study, we explored the potential function of Myo1b in CRC and confirmed that Myo1b facilitated CRC progression and angiogenesis by inhibiting autophagic degradation of HIF-1α, suggesting that Myo1b acts as a tumor promoter in CRC." (PMID 36347835, 2022). "Accompanied investigations disclosed the down-regulation of HIF-1α and c-Myc, suggesting a close relationship between epigenetic regulation and tumor hypoxia." (PMID 36516252, 2022). "Hypoxia and HIF-1α forward tumor migration along with infiltration and distant metastasis via different signaling cascades." (PMID 35417854, 2022). "Tumor-cell-derived lactate triggers the expression of vascular endothelial growth factor, Arg1, and the M2-like polarization of TAMs, mediated by HIF-1α, and promotes tumor growth." (PMID 35224683, 2022). "Western blotting of tumor cell lysates indicated that hypoxia‐inducible factor 1α (HIF‐1α) protein expression was considerably upregulated in the MKN45–CAF co‐culture compared with MKN45 cells alone." (PMID 35901491, 2022). "Among them, HIF-1α regulates the expression of genes that are involved in tumor progression, aggressiveness, and metastasis." (PMID 36145513, 2022). "In conclusion, in this study, our findings highly demonstrate the expression landscape of HIF1α in human pan-cancer and identify the relationship between HIF1α expression levels and tumor immune infiltration and HIF1α-targeting drugs." (PMID 35860430, 2022). "Related to the specific tumor microenvironments, HIF-1α (ubiquitously expressed) and HIF-2α (selectively expressed in distinct cell populations) play different roles in tumorigenesis, but they are considered to be the main regulators of the hypoxic response." (PMID 35054779, 2022). "Tumour HIF-1α status correlated to histological grade, with a higher frequency of HIF-1α positivity among high-grade tumours (p < 0.0001)." (PMID 35140341, 2022). "HIF1A has a regulatory role in promoting tumor progression, likely through hypoxia-induced VEGF-A expression pathways." (PMID 35252204, 2022). "Experiments have shown that the7-OH-Neo A has anti-tumor activities such as anti-tumor angiogenesis, proliferation, invasion, and migration, and can be used as a promising HIF-1α inhibitor in the future." (PMID 36139386, 2022). "Xenograft models established from CA-AKT-expressing GC cells exhibited a higher incidence of tumor formation with larger volumes, higher micro-vessel density, and HIF-1α expression." (PMID 35681691, 2022). "Pre-clinical experiments show that inhibition of HIF-1α effectively prevents immune suppression and improves anti-tumor immunity." (PMID 35805044, 2022). "The results show that, in addition to tumor cells, in vivo HIF-1α inhibition can also suppress PD-L1 on tumor-infiltrating myeloid cells, and these effects persist in the context of anti–CTLA-4 therapy." (PMID 35239514, 2022). "WNT7b and HIF-1α expression have a positive correlation with the induced expression of VEGF which plays an important role in the tumor angiogenesis." (PMID 36679900, 2022). "In the 258 cells analyzed from this tumor tissue, PD-L1 expression correlated significantly with HIF1α expression, although PD-L1 expression correlated stronger with STAT1." (PMID 34268602, 2022). "al., investigated the effects of HIF-1α and its downstream regulator of embryogenesis and tumour progression β-catenin." (PMID 36233505, 2022).